MACF1 (microtubule actin crosslinking factor 1)
Diseases named in the same sentence as MACF1 in open-access papers (continued):
Sharing a sentence is not in itself a finding about the gene and the disease.
amyloidosis (1 paper, 2024). A disorder characterized by the localized or diffuse accumulation of amyloid protein in various anatomic sites. "Additional astrocyte hub genes in the ETC, including NRXN1, CADM1, MACF1, MAGI2, LRP4, GJA1 and ADGRL3, have been identified as markers of a reactive astrocyte state, implicating them in amyloidosis, regulation of neuroinflammation, cellular interactions." (PMID 38913039, 2024).
atherosclerosis (1 paper, 2022). A disease characterized by the build-up of fatty material and calcium deposition in the arterial wall resulting in partial or complete occlusion of the arterial lumen. "The fluid shear stress and atherosclerosis pathway was presumed as the most important pathway for MACF1 to regulate osteogenesis." (PMID 36207684, 2022).
autosomal dominant non-syndromic hearing loss (1 paper, 2025). "In conclusion, we report a novel candidate gene (MACF1) for autosomal dominant non-syndromic hearing loss (ADNSHL)." (PMID 40001331, 2025). "Here, we add to this growing number by implicating MACF1 (OMIM # 608271), as a novel candidate gene for autosomal dominant non-syndromic hearing loss (ADNSHL)." (PMID 40001331, 2025).
bladder cancer (1 paper, 2014). "Some cancer-associated DSGs in our result were reported in the other cancers but not reported in the bladder cancer yet, such as PDGFA, MACF1, ADD3 and NUMB." (PMID 24622401, 2014).
bladder tumors (1 paper, 2019). "Specifically, higher rates of FAT4 mutation and MACF1 mutation in bladder tumors with high risk score were found compared with tumors with low risk score." (PMID 31737111, 2019). "Higher rates of FAT4 mutation and MACF1 mutation in bladder tumors with high risk score were found compared with tumors with low risk score." (PMID 31737111, 2019). "Moreover, we also revealed higher mutation rates of FAT4 and MACF1 in bladder tumors with higher risk score." (PMID 31737111, 2019).
cardiac hypertrophy (1 paper, 2013). "Contrary to our expectations, MACF1 KO significantly exacerbated TAC-induced cardiac hypertrophy, as indicated by greater increase of LV weight and the ratio to bodyweight or tibia length (not shown) in MACF1 KO mice." (PMID 24086300, 2013). "Because PKCα contributes to cardiac hypertrophy and LV dysfunction in pressure overload, while loss of caveolin 3 promotes cardiomyopathy, the altered expression and distribution of these proteins may help explain the increased pathological hypertrophy observed in MACF1 KO mice after TAC." (PMID 24086300, 2013).
congestive heart failure (1 paper, 2013). Failure of the heart to pump a sufficient amount of blood to meet the needs of the body tissues, resulting in tissue congestion and edema. "In support of an accelerated transition into congestive heart failure, MACF1 KO mice had significantly greater pulmonary congestion as indicated by lung weight to body weight ratio." (PMID 24086300, 2013).
Crohn disease (1 paper, 2022). A gastrointestinal disorder characterized by chronic inflammation involving all layers of the intestinal wall, noncaseating granulomas affecting the intestinal wall and regional lymph nodes, and transmural fibrosis. "The opposite direction of the expression of MACF1 transcript between non-responders relative to responders in healthy and inflamed colon tissue additionally suggests an important role of this gene in anti-TNF response in Crohn’s disease." (PMID 36145641, 2022).
diabetes mellitus (1 paper, 2018). A metabolic disorder characterized by abnormally high blood sugar levels due to diminished production of insulin or insulin resistance/desensitization. "Increased expression of MACF1, together with supporting predicted mRNA-miRNA interactions as well as reduced expression of RNYs in platelets, may reflect subclinical platelet activation in uncontrolled diabetes mellitus." (PMID 30519591, 2018).
fragile X syndrome (1 paper, 2024). A genetic syndrome caused by mutations in the FMR1 gene which is responsible for the expression of the fragile X mental retardation 1 protein. "In contrast, our patient with a MACF1 mutation did not demonstrate comparable psychiatric impairments, and the EEG discharges are different from those found in Fragile X Syndrome." (PMID 39781307, 2024).
head and neck cancer (1 paper, 2019). A primary or metastatic malignant neoplasm affecting the head and neck. "Relatively frequent mutations were also detected in several other IntOgen-defined cancer drivers such as MGA, PABPC3, NR4A2, NCOR1 and MACF1; of these PABPC3, NR4A2, NCOR1 and MACF1 are detected as mutational cancer drivers in head and neck cancer in IntOgen." (PMID 31427592, 2019).
hepatocellular carcinoma (1 paper, 2022). A malignant tumor that arises from hepatocytes. "Among these SMGs, MACF1 (5.17%, 18/348) and AXIN1 (0.86%, 3/348, all of the three patients were with iCCA), which is commonly considered as one of the potential drivers in hepatocellular carcinoma (HCC), are two interactive components of the β-catenin/Wnt signaling pathway." (PMID 35650238, 2022).
hereditary sensory autonomic neuropathy (1 paper, 2016). "This hypothesis is attractive because the well-conserved mammalian spectraplakin Dystonin is already linked to a neurodegenerative disease (type VI hereditary sensory autonomic neuropathy; OMIM #614653;), and its paralogue ACF7/MACF1 plays important roles during brain development." (PMID 27501441, 2016).
inflammatory bowel disease (1 paper, 2022). A spectrum of small and large bowel inflammatory diseases of unknown etiology. "It was also proven that MACF1 regulates the molecular mechanism of cytoskeletal coordination and subsequent cell adhesion regulation in intestinal wound repair, and contributes to the development of inflammatory bowel disease." (PMID 36145641, 2022).
laryngeal squamous cell carcinoma (1 paper, 2025). A squamous cell carcinoma that arises from the larynx. "A report revealed that circular MACF1 RNAs (circ_MACF1) were expressed substantially in laryngeal squamous cell carcinoma (LSCC) tissues, cells, and exosomes isolated from LSCC cells." (PMID 40244019, 2025).
lissencephaly 9 with complex brainstem malformation (1 paper, 2025). "Currently, variants in MACF1 are causally linked to Lissencephaly 9 with complex brainstem malformation (LIS9)." (PMID 40001331, 2025).
metastasis (1 paper, 2023). The spread or migration of cancer cells from one part of the body (where they first appeared) to another.
metastatic tumors (1 paper, 2022). "Among these, FRAS1, PTPRC, MACF1 and MYH8 mutations have been found to be more enriched in other metastatic tumors." (PMID 36033490, 2022).
myeloma (1 paper, 2026). "According to the HPA, MACF1 was expressed across 34 myeloma cell lines, with protein expression confirmed in 12 of them." (PMID 41596441, 2026).
Myocardial fibrosis (1 paper, 2013). "Myocardial fibrosis however, as evidenced by sirus red stain, was increased in response to TAC to a similar extent in WT and MACF1 KO mice." (PMID 24086300, 2013).
non-small cell lung carcinoma (1 paper, 2018). A group of at least three distinct histological types of lung cancer, including non-small cell squamous cell carcinoma, adenocarcinoma, and large cell carcinoma. "One of the first studies linking MACF1 to cancer was performed using alternative splicing microarray profiling that revealed transcript alterations of MACF1 in non-small cell lung cancer." (PMID 29373494, 2018).
postmenopausal osteoporosis (1 paper, 2026). Metabolic disorder associated with fractures of the femoral neck, vertebrae, and distal forearm. "MACF1 deficiency exacerbated age‐related osteoporosis, while MACF1 overexpression rescued age‐related and postmenopausal osteoporosis by promoting osteoblastic cell differentiation." (PMID 41363907, 2026).
Premature ovarian insufficiency (1 paper, 2025). Amenorrhea due to loss of ovarian function before the age of 40. "Further analysis of the novel candidate genes in premature ovarian insufficiency, including MACF1, is pending." (PMID 40244019, 2025).
proliferative diabetic retinopathy (1 paper, 2025). Advanced retinopathy due to diabetes mellitus characterized by the formation of new vessels in the retina. "MACF1 theoretically functions as an RNA-binding protein that regulates the alternative splicing of cell cycle-associated genes in proliferative diabetic retinopathy, and will therefore be a promising treatment target for the disease." (PMID 40244019, 2025).
serous ovarian carcinoma (1 paper, 2025). "A study reported the gene expression of MACF1 in fresh tumor tissues and the associated normal tissues of eighteen serous ovarian cancer (SOC) patients by quantitative RT-PCR, and the protein expression of MACF1 from paraffin-embedded SOC tissues and paratumor tissues by immunohistochemistry." (PMID 40244019, 2025).
cancer (24 papers, 2012 to 2026). A tumor composed of atypical neoplastic, often pleomorphic cells that invade other tissues. "Some less-frequent mutations of cancer-related genes were also discovered, including MACF1 (14.7%; 5/34)." (PMID 40244019, 2025). "It has also been shown that the MACF1 mutation was correlated with Wnt/β-catenin signaling in cancer." (PMID 29587367, 2018). "In cancer, MACF1 has been shown to promote the expression of Wnt-responsive genes, contributing to cell proliferation, migration, and signal transduction." (PMID 41596441, 2026). "MACF1 is also involved in pathological conditions, including various types of cancer and other human diseases." (PMID 40244019, 2025). "MACF1 is also involved in pathological conditions, which include neuromuscular diseases, neurodegenerative diseases, and cancers." (PMID 40244019, 2025). "The TEAD4/AP-1/SRC complex modulates a set of genes, including DOCKs (Dedicator of cytokinesis), CDH2 (Cadherin 2), and MACF1(Microtubule Actin Crosslinking Factor 1), to regulate cancer metastasis." (PMID 35602596, 2022). "We will review over two decades of research aimed at understanding the molecular, physiological and pathological roles of MACF1, with a focus on its roles in developmental and cancer." (PMID 33816492, 2021). "In an effort to enhance therapeutic benefit, combination of traditional therapies with inhibition of MACF1 was tested in this type of cancer." (PMID 33816492, 2021). "The characterization of MACF1 function in cancer has been primarily limited to high-throughput genomics and proteomics approaches." (PMID 29373494, 2018). "We also found within the most altered nodes, genes that have not been previously reported in the context of TNBC but have been reported in other cancer types, for example, the Microtubule Actin Crosslinking Factor 1 (MACF1) in chromosome 1, and olfactomedin 2 (OLFM2) in chromosome 19." (PMID 40688355, 2025). "In addition to the growing list of pathologies associated with MACF1 genetic alterations, aberrant expression of MACF1 is also related to various human cancers." (PMID 33816492, 2021). "Among them, MACF1 is a pan-cancer driver gene, which is related to cell adhesion function." (PMID 31570735, 2019). "Few investigations to date have examined MACF1 function in cancer biology." (PMID 29373494, 2018). "As MACF1 is critical in mediating the Wnt signaling pathway, it is suggested that MACF1 may function in cancers through Wnt signaling." (PMID 29587367, 2018). "All these findings demonstrate that MACF1 is a promising target for cancer diagnosis and therapy." (PMID 29587367, 2018). "MACF1 has recently received increasing attention for its role in various cancers." (PMID 29587367, 2018). "In addition, MACF1 has also been shown to be a target of microRNA in both hepatocellular carcinoma and malignant tumors." (PMID 29587367, 2018). "This could particularly be advantageous in treating a disease like cancer, for which evidence exists that plakin proteins such as MACF1 and plectin may act as oncoproteins." (PMID 29373494, 2018). "Among genes downregulated by clofibrate, the major part belonged mainly to functional groups: “cancer” (STIP1, HNRNPA1, VIL1, and CDH1) and “cellular assembly and organization” (CLASP1 and MACF1)." (PMID 22619672, 2012). "Since MACF1 can act as a positive regulator in the Wnt receptor signaling pathway and function through the oncogenic MAPK signaling pathway, it has been selected as a novel potential target in several cancers." (PMID 30065750, 2018).
cancer (continued). "Similar to BPAG1, in most of the datasets, MACF1 mRNA levels are significantly decreased in cancer as opposed to normal tissues." (PMID 29587367, 2018). "In addition, 1 SNP was detected in KMT2C, a BC oncogene, and 9 others were detected in or near 10 genes (SERAC1, DAGLB, MACF1, NVL, FBXW4, FANK1, KCTD4, CAVIN1; ATP6V0A1 and ZBTB20-AS1) previously associated with non-BC cancers." (PMID 35589867, 2022). "MACF1 has no direct relation with cancer, it has been reported to function in the Wnt signaling pathway and to be associated with a complex containing Axin, beta-catenin, glycogen synthase kinase 3 (GSK3B), and adenomatous polyposis coli (APC), which have been linked to tumorigenesis." (PMID 24622401, 2014). "Careful analysis of GBM from different stages revealed that MACF1 is highly expressed in grade IV GBM but not in surrounding normal tissues or lower grade GBM, revealing its potential as a prognostic marker for this type of cancer." (PMID 33816492, 2021).
tumor (21 papers, 2008 to 2025). "The patient had ten mutated genes in the tumor DNA and a total of 60 mutated spots, and only one mutated gene, MACF1, was detected in both tumor DNA and cfDNA." (PMID 36779847, 2023). "MACF1 mutation was also found to upregulate the mTOR signaling pathway and change tumor immune microenvironment." (PMID 37589509, 2023). "Patients with MACF1 mutation harbored a poor prognosis and higher tumor mutation burden score." (PMID 37589509, 2023). "Consistent with the role of MACF1 in Wnt signaling, these anti-tumorigenic effects were also associated with a significant down-regulation of Wnt signaling and its mediators associated proteins, Axin1 and β-catenin, whose dysregulation is well known to be involved in tumor progression." (PMID 33816492, 2021). "A literature review revealed that MACF1 significantly induced PI3K/AKT and GSK3β activities and was closely associated with tumor metastasis." (PMID 40084246, 2025). "Previous study has shown that MACF1 is substantially expressed in GBM tumor tissues instead of the low-grade oligodendroglioma, medulloblastoma, and the counterpart normal brain tissues." (PMID 40244019, 2025). "LRRC1 depletion inhibited the xenograft tumor growth of HL-60 cells in nude mice, and downregulated MACF1 expression as well as β-catenin/c-Myc signaling in tumor tissues." (PMID 40244019, 2025). "Upregulation of genes that encode for proteins known to increase T and B cell trafficking to tumors (CCL19, CXCL9), migration (MACF1) and tumor cell killing (GZMB) correlated with responses." (PMID 38519913, 2024). "The sensitivity of the mutation status of cfDNA to predict mutation in tumor samples was highest in FAT4 (88.9%), followed by MACF1 (80%), CDH1 (75%) and PLB1 (75%)." (PMID 36779847, 2023). "The expression levels of RAMP-AS1, miR-296-5p, CD44, CCND3, NCALD and MACF1 were detected in 40 tumor and adjacent tissue samples via RT-qPCR." (PMID 33281971, 2021). "Reverse transcription-quantitative PCR assays revealed that RAMP2-AS1, CD44, CCND3, NCALD and MACF1 expression was lower in tumor tissues than in normal tissues, while miR-296-5p expression was higher in tumor tissues compared with in normal tissues." (PMID 33281971, 2021). "The expression of MACF1 was higher in tumor tissues than in paratumor tissues." (PMID 40244019, 2025). "Tumor growth and lung metastasis were suppressed in MACF1 RNAi-B16F10-cell-injected mice." (PMID 40244019, 2025). "Notably, MACF1 and plectin act as tumor promoters in CRC by affecting the cytoskeleton and intercellular interactions, thereby promoting cell migration." (PMID 41169522, 2025). "MACF1 is an important molecule that adjusts the invasive and metastatic potential of tumor cells." (PMID 37993901, 2023). "Additionally, lenti-circ_MACF1-transduced tumors had markedly fewer cells stained for Ki67 staining than the controls under gefitinib, reinforcing the repression of tumor growth of circ_MACF1 overexpression." (PMID 34996416, 2022). "The in vivo experiments implied that tumor growth under gefitinib may be regulated by the circ_MACF1/miR-942-5p/TGFBR2 axis." (PMID 34996416, 2022). "Most of the significantly up-regulated genes were involved in cell cycle/mitosis/cell division (e.g., TTK, CENPF, NEK2), while many of those down-regulated were involved in cell adhesion/cell cycle arrest (e.g., ADRB2, APLP2, MACF1), consistent with a role of these genes in neoplasia development." (PMID 18297132, 2008).
tumor (continued). "Finally we demonstrate the tumour-suppressive role of METTL14, a major RNA N6-adenosine methyltransferase (m6A), and illustrate that its loss-of-function mutation R298H may act through m6A modification on potential driver gene MACF1." (PMID 35650238, 2022). "Conversely, proteins of interest in tumor-bearing rats that were elevated following OKN-007 treatment included ABCA6, ADAMTS18, VWA8, MACF1, and LAMA5." (PMID 35053843, 2022). "Conversely, proteins of interest in tumor-bearing rats elevated following OKN-007 treatment included ABCA6, ADAMTS18, VWA8, MACF1, and LAMA5." (PMID 35053843, 2022). "Overexpression of circ_MACF1 repressed proliferation, migration, invasion, and promoted apoptosis and gefitinib sensitivity of A549/GR and PC9/GR cells in vitro, as well as inhibited tumor growth under gefitinib in vivo." (PMID 34996416, 2022). "The expression levels of CD44, CCND3, NCALD, MACF1 and KCTD15 were downregulated in the vast majority of LUAD histological subtypes compared with in normal samples; additionally, they were differentially expressed according to tumor stage and nodal metastasis status." (PMID 33281971, 2021). "Furthermore, the expression levels of CD44, CCND3, NCALD, MACF1 and KCTD15 were downregulated in the vast majority of LUAD histological subtypes compared with in normal samples, and they were differentially expressed according to tumor stage and nodal metastasis status." (PMID 33281971, 2021).
neurodegenerative disease (6 papers, 2016 to 2025). A disorder of the central nervous system characterized by gradual and progressive loss of neural tissue and neurologic function. "Recent studies show that MACF1 is involved in multiple cellular functions such as neuron development and epidermal migration, and is the molecular basis for many degenerative diseases." (PMID 32143362, 2020).